SLC25A37 (solute carrier family 25 member 37)
Description:
Mitochondrial iron transporter that specifically mediates iron uptake in developing erythroid cells, thereby playing an essential role in heme biosynthesis.
Synonyms: MFRN; MSCP; HT015; MFRN1
Tractability: Antibody: UniProt predicts a signal peptide or a membrane-spanning region.
Gene: Protein-coding gene on chromosome 8 (23,528,956 to 23,575,463, forward strand). Ensembl gene ENSG00000147454.
Subcellular location: Mitochondrion inner membrane
Subcellular location (Human Protein Atlas): Mitochondria; Cytosol
Pathways (Reactome):
Metabolism: Mitochondrial iron-sulfur cluster biogenesis
Gene Ontology:
Molecular function: iron ion transmembrane transporter activity; protein binding; ferrous iron transmembrane transporter activity
Biological process: iron import into the mitochondrion; positive regulation of hemoglobin biosynthetic process
Cellular component: mitochondrion; mitochondrial inner membrane
Genetic constraint (gnomAD): Loss-of-function variants: 17 observed, 29.68 expected, observed/expected ratio (o/e) 0.57, 90% interval 0.39 to 0.86. The upper end of that interval is the gene's LOEUF score, 0.86, which puts it in group 3 of 6, group 1 being the genes least tolerant of losing a copy. Missense variants: 404 observed, 468.69 expected, observed/expected ratio (o/e) 0.86, 90% interval 0.79 to 0.94. Synonymous variants: 222 observed, 195.09 expected, observed/expected ratio (o/e) 1.14, 90% interval 1.02 to 1.27.
Homologues: Orthologues: chimpanzee SLC25A37 (99% identical), macaque SLC25A37 (99% identical), guinea pig SLC25A37 (94% identical), rat Slc25a37 (92% identical), mouse Slc25a37 (91% identical), dog SLC25A37 (83% identical), zebrafish slc25a37 (67% identical), tropical clawed frog slc25a37 (67% identical), rabbit SLC25A37 (52% identical). Paralogues in human: SLC25A28 (66% identical), SLC25A12 (26% identical), SLC25A13 (26% identical), SLC25A18 (25% identical), SLC25A23 (24% identical), SLC25A24 (23% identical), SLC25A19 (22% identical), SLC25A25 (22% identical), SLC25A38 (22% identical), SLC25A48 (22% identical), SLC25A21 (22% identical), SLC25A22 (22% identical), and 37 more.
Diseases named in the same sentence as SLC25A37 in open-access papers:
SLC25A37 is named in the same sentence as 53 diseases in open-access papers, as found by Europe PMC text mining. Sharing a sentence is not in itself a finding about the gene and the disease. The quoted sentences say what the papers report.
anemia (7 papers, 2010 to 2023). A reduction in the number of red blood cells, the amount of hemoglobin, and/or the volume of packed red blood cells. "Although HEBP2 and SLC25A37 have been described to be involved in different diseases such as cancer, anemia, porphyria, or depression, we focused on TFAM for further studies due to its widely observed implication in different neurodegenerative disorders, PD being among them." (PMID 36674978, 2023). "The selective deletion of SLC25A37 in adult hematopoietic tissues leads to severe anemia, suggesting that the lethality of SLC25A37 depletion might be due to defects in hematopoiesis." (PMID 33117818, 2020). "More directly, erythroblasts are themselves significantly dependent on proper iron homeostasis controlled by IRP2 and on successful iron acquisition mediated by transferrin receptor 1 (TfR1) and mitoferrin-1 (or SLC25A37), as shown by anemias that develop when they are deficient in model organisms." (PMID 20862391, 2010). "However, in the subjects with refractory anemia and ring sideroblasts (RARS), increased expression of mitoferrin 1 (SLC25A37) in bone-marrow mononuclear cells was found." (PMID 29623423, 2018).
pancreatic cancer (7 papers, 2020 to 2023). "In patients with pancreatic cancer, the high expression of SLC25A37 is associated with poor prognosis." (PMID 33489900, 2020). "Studies have shown that SLC25A37 is related to mitochondrial iron accumulation in pancreatic cancer." (PMID 36937929, 2023). "After identifying FBXL5, SLC25A28, and SLC25A37 as substrate RNAs of ALKBH5, we further investigated the relevant mechanism associated with pancreatic cancer progression." (PMID 34733841, 2021). "Mechanistically, the RNA stabilities of FBXL5 and SLC25A28, and the AS of SLC25A37 were affected, which led to their upregulation in pancreatic cancer cell line." (PMID 34733841, 2021). "Interestingly, the expression of SLC25A37 in patients with pancreatic cancer correlated negatively with patient survival, yet the expression of SLC25A28 did not correlate with survival." (PMID 36359860, 2022). "For instance, ALKBH5 overexpresses in pancreatic cancer cell line and regulates RNA stabilities of LC25A28 and SLC25A37 through modulating regulators of iron metabolism and underscores the multifaceted role of m6A in pancreatic cancer." (PMID 36781839, 2023).
breast carcinoma (4 papers, 2019 to 2026). "SLC25A37 was significantly over-expressed in high cytotoxicity patients and loss of TIM50 suppressed tumor cell growth and induced apoptosis in breast cancer and loss of TIM50 suppressed tumor cell growth and induced apoptosis in breast cancer." (PMID 34381023, 2021). "In vivo validation using immunohistochemistry on clinical samples from 10 breast cancer patients with ovarian metastases confirmed that GPR183, BHLHE41, and CD83 were highly expressed in tumor tissues, while SLC25A37 and SELL were highly expressed in adjacent normal tissues." (PMID 42101520, 2026).
erythropoietic protoporphyria (4 papers, 2021 to 2023). A rare congenital metabolic disorder characterized by an inborn error of porphyrin-heme biosynthesis. "Previous studies reported that patients with erythropoietic protoporphyria or myelodysplastic syndrome exhibited a significant decrease in the levels of the normal SLC25A37 isoform, accompanied with an increase in its abnormal isoform encoding a defective protein." (PMID 34733841, 2021).
osteosarcoma (4 papers, 2020 to 2025). A usually aggressive malignant bone-forming mesenchymal neoplasm, predominantly affecting adolescents and young adults. "Interestingly, our work revealed that mitochondrion-mediated iron accumulation increased ROS production in both osteosarcoma cell lines, whereas knock-down of mitoferrin 1 (SLC25A37) and mitoferrin 2 (SLC25A28) decreased this phenomenon." (PMID 32831652, 2020). "Mitochondrial iron transporters mitoferrin 1 (SLC25A37) and mitoferrin 2 (SLC25A28)-mediated iron accumulation increase ROS mediated-carcinogenesis in osteosarcoma." (PMID 36185202, 2022).
major depressive disorder (3 papers, 2022 to 2024). An episode of depression lasting two or more weeks without an intervening episode of mania. "Compelling evidence supports the consistent downregulation of SLC25A37 in individuals afflicted with major depressive disorder (MDD), heralding its potential utility as a biomarker for MDD diagnosis and a propitious target for subsequent therapeutic and diagnostic interventions." (PMID 38801430, 2024).
rhabdomyosarcoma (3 papers, 2022 to 2024). A rare aggressive malignant mesenchymal neoplasm arising from skeletal muscle. "RNA sequencing revealed the downregulation of SLC25A37 mRNA and protein expression, as well as mitochondrial dysfunction and cell death in human rhabdomyosarcoma RD cells overexpressing miR-7." (PMID 36359860, 2022). "In rhabdomyosarcoma (RMS), miR-7 exerts an anti-tumor effect by targeting mitochondrial proteins SLC25A37 and TIMM50, ultimately inducing necrosis." (PMID 38383747, 2024). "In rhabdomyosarcoma, miR-7 is reported to downregulate TIMM50 and SLC25A37 and thus promote mitochondrial dysfunction, resulting in cell necroptosis." (PMID 36349193, 2022).
myelodysplastic syndrome (2 papers, 2021 to 2022). A clonal hematopoietic disorder characterized by dysplasia and ineffective hematopoiesis in one or more of the hematopoietic cell lines. "Suggesting the regulation of SLC25A37 by the splicing factor SF3B1, a splice variant of SLC25A37 was detected in the bone marrow cells of patients with myelodysplastic syndrome (MDS) and a mutation SF3B1, the gene most often mutated in MDS." (PMID 36359860, 2022).
ovarian carcinoma (2 papers, 2023). A malignant neoplasm originating from the surface ovarian epithelium. "Furthermore, GEPIA database analysis showed that only four genes, PIK3R1, JUNB, RHOBTB2, and SLC25A37, were expressed at low level in ovarian cancer and were correlated positively with YTHDC1." (PMID 37781028, 2023).
Sepsis (2 papers, 2023 to 2025). Sepsis is defined as life-threatening organ dysfunction caused by a dysregulated host response to infection. "The expressions of HIF1A and SLC25A37 were significantly higher in the sepsis group compared with that in the control group." (PMID 36937929, 2023). "Subsequently, we measured the mRNA expression of SLC25A22, SLC25A33, and SLC25A37, along with that of pro-inflammatory cytokines, including TNF-α, IL-6, and IL-1β, in CD14+ monocytes from sepsis patients with liver abscesses." (PMID 40384854, 2025). "This led to the identification of two iron metabolism genes related to sepsis prognosis (HIF1A and SLC25A37)." (PMID 36937929, 2023). "Common differential expression of IMRGs was identified in blood monocytes and myocardium between sepsis and control groups, among which HIF1A and SLC25A37 might predict prognosis in septic cardiomyopathy." (PMID 36937929, 2023).
autism (1 paper, 2024). Persistent deficits in social interaction and communication and interaction as well as a markedly restricted repertoire of activity and interest as well as repetitive patterns of behavior. "They identified several genes, including SLC25A37, with differential methylation in individuals with autism compared to healthy controls." (PMID 39061976, 2024). "Methylation affects gene expression, suggesting that the SLC25A37 gene may be differentially expressed in individuals with autism." (PMID 39061976, 2024).
cataract (1 paper, 2025). Partial or complete opacity of the crystalline lens of one or both eyes that decreases visual acuity and eventually results in blindness. "Reassuringly, as part of this study we identified several gene pairs such as SLC25A37/SLC25A28 and CNOT7/CNOT8 that represent attractive targets for further drug development, with Slc25a28 knockout mice being viable and fertile with no overt phenotypes, other than cataracts in some mice." (PMID 40968372, 2025).
iron overload (1 paper, 2024). "Intracellular iron is transported to mitochondria via SLC25A37 and SLC25A28, and thus impaired intracellular and mitochondrial iron homeostasis has been identified as a hallmark of iron overload, which in turn accelerates the process of iron overload." (PMID 39767635, 2024).
Obesity (1 paper, 2024). Accumulation of substantial excess body fat. "Resistance to obesity in NR mice was associated with 4.9-fold upregulated mitoferrin 1 (Slc25a37), an essential mitochondrial iron importer." (PMID 38276304, 2024). "When compared to the HFD controls, obesity-resistant NR mice showed the capacity to significantly upregulate mitoferrin 1 (Slc25a37, 4.9-fold) and uncoupling protein 2 (Ucp2, 2.4-fold)." (PMID 38276304, 2024).
sarcoma (1 paper, 2020). A usually aggressive malignant neoplasm of the soft tissue or bone. "HK2, GLUT1, PGK1, ENO1 and PKM were found positive correlation with SLC25A37 in sarcoma patients." (PMID 32831652, 2020).
tumor (15 papers, 2020 to 2026). "Our investigation has implicated SLC25A37 in fostering the proliferation and migration of tumor cells in ccRCC." (PMID 38801430, 2024). "In the TCGA dataset, SLC25A37 was significantly upregulated in tumor tissues, while CPPED1 and KCNJ15 were significantly upregulated in adjacent non-tumor tissues." (PMID 38801430, 2024). "The tumor-suppressor roles of SLC25A37 and SLC25A28 have been confirmed since they were involved in tumor cell growth, ROS production, mitochondrial iron uptake, and ferroptosis." (PMID 35936737, 2022). "In rhabdomyosarcoma (RMS), miR-7 showed the anti-tumor effect to induce necroptosis by targeting mitochondrial proteins SLC25A37 and TIMM50." (PMID 34381023, 2021). "For several genes, most notably CNOT7, GDI1 and SLC25A37, there are a subset of tumours that showed homozygous deletion and thus inhibition/suppression of CNOT8, GDI2 or SLC25A28, respectively, would be predicted to provoke cellular lethality/reduced cancer cell fitness." (PMID 40968372, 2025). "Single-cell RNA sequencing analysis unveils the marked enrichment of SLC25A37 in tumor cells." (PMID 38801430, 2024). "However, despite of positive regulation of ALKBH5 on SLC25A28 and SLC25A37 observed here, we found that these two proteins were overexpressed in the tumor cells of PDAC." (PMID 34733841, 2021). "SLC25A37 mediated by the PINK1-PARK2 pathway increases mitochondrial iron accumulation, which leads to the HIF1A-dependent Warburg effect and AIM2-dependent inflammasome activation in tumor cells." (PMID 36937929, 2023). "In miR-7 transfected RMS cells, miR-7 acts via its target mitochondrial proteins solute carrier family 25 member 37 (SLC25A37) and translocase of inner mitochondrial membrane 50 (TIMM50) to promote apoptosis and necroptosis, and also impair tumour invasion and lung metastasis." (PMID 36765536, 2023). "As shown, of the various tumor pathological grades, the expression levels of SLC25A4 (P < 0.01), SLC25A11 (P < 0.0001), SLC25A24 (P < 0.01), SLC25A37 (P < 0.01), SLC25A42 (P < 0.01), SLC25A43 (P < 0.0001), SLC25A44 (P < 0.05) and SLC25A45 (P < 0.05) were significantly different." (PMID 36514121, 2022). "The degradation of SLC25A37 can be mediated by the PINK1-PARK2 pathway to increase the accumulation of iron in mitochondria, which leads to the activation of the inflammasome in tumor cells." (PMID 33489900, 2020). "Previous study found impaired PINK1 and PRKN expression could promote the degradation of SLC25A37 and SLC25A28 and increase the mitochondrial iron accumulation, which lead to AIM2-mediated HMGB1 release that further induced expression of CD274/PD-L1 in tumor cells." (PMID 36612054, 2022).
cancer (14 papers, 2015 to 2025). A tumor composed of atypical neoplastic, often pleomorphic cells that invade other tissues. "In binary analyses, replication revealed POTEB3 rs2605913 (p = 2.8 × 10-8), while meta-analysis (n = 13,652) uncovered SLC25A37 rs952825245 (p = 5.15 × 10-12), a locus associated with cancer and vitamin D signaling." (PMID 41096749, 2025). "SLC25A3 and SLC25A37 encode two critical mitochondrial copper transporters, which potentially regulate cuproptosis in cancers." (PMID 36276096, 2022). "Additionally, G0S2 and SLC25A37 were identified as risk factors for multiple types of cancer." (PMID 37408763, 2023). "We show that SLC25A28 is an attractive target since its synthetic lethal paralog partner SLC25A37 is homozygously deleted pan-cancer." (PMID 40968372, 2025). "Real-time quantitative PCR (RT-qPCR) was engaged to scrutinize the differential expression of SLC25A37 across cancer and paracancer tissues, as well as diverse cell lines." (PMID 38801430, 2024). "Researchers also found that SLC25A37 regulated the proliferation and apoptosis in carcinoma through mitochondrion mediated iron channel." (PMID 33686958, 2021).
infection (3 papers, 2013 to 2018). The state of being infected such as from the introduction of a foreign agent such as serum, vaccine, antigenic substance or organism. "The highly significant modulation of these genes and in other genes related to channels/transporters such as Abca1 and Slc25a37 may be indicative of a metabolic shift in the host epithelium due to infection with C. rodentium." (PMID 29339782, 2018).
Hematological Disease (1 paper, 2019). "The network was categorized as “Small Molecule Biochemistry,” “Hematological Disease,” and “Metabolic Disease,” which were composed of down-regulated genes that were listed in the top 2 and 3 networks of A.SW mouse spleen: Gata1-related genes and transporter genes (Abcb6, Slc25a39, and Slc25a37)." (PMID 30941144, 2019).
SLC25A37 also shares sentences with these, for which no sentence is quoted: melanoma (5 papers); Alzheimer disease (3); hepatocellular carcinoma (3); hypochromic anaemia (2); hypothyroidism (2); liver cancer (2); autoimmune disease (1); benign prostatic hyperplasia (1); cardiovascular diseases (1); cholestasis (1); Cirrhosis (1); depression (1); essential thrombocytosis (1); Friedreich ataxia (1); glioblastoma (1); glioma (1); head and neck cancer (1); heart diseases (1); hemorrhage (1); iron deficiency (1); liver abscesses (1); lung carcinoma (1); malaria (1); metabolic disease (1); neurological diseases (1); Parkinson disease (1); pneumonia (1); polycythemia vera (1); porphyria (1); renal angiomyolipoma (1).
A further 4 diseases each share a sentence with SLC25A37 in 1 paper.